COL11A1 (collagen type XI alpha 1 chain)
Diseases named in the same sentence as COL11A1 in open-access papers (continued):
Sharing a sentence is not in itself a finding about the gene and the disease.
breast carcinoma (continued). "Therefore, we screened five genes related to the immune pathway associated with COL11A1 in breast cancer and constructed a signature to assess the prognosis of the patient based on these genes." (PMID 36389832, 2022). "The graph shows the top 50 genes positively or negatively associated with COL11A1 in breast cancer." (PMID 36160004, 2022). "Furthermore, we also found that COL11A1 was positively correlated with risk factors in the breast cancer TME." (PMID 36389832, 2022). "In this study, we found that COL11A1 was significantly up-regulated in breast cancer tissues, whether in independent samples or paired samples, and the high expression of COL11A1 was significantly associated with poor prognosis of breast cancer patients." (PMID 36160004, 2022). "Furthermore, we applied these techniques in breast cancer tissues in order to use the obtained quantitative data to determine any existing significant correlation between the differential expression of COL11A1 variants and clinicopathological features of these patients." (PMID 26466668, 2015). "In this study, we investigate the role of COL11A1 in breast cancer development and assess its clinical relevance in diagnosing and prognosticating the disease." (PMID 39845732, 2025). "In conclusion, our findings clearly demonstrate a significant correlation between breast cancer progression and alterations in COL11A1 expression." (PMID 39845732, 2025). "In a larger cohort, primary breast cancers (n = 107) had significantly elevated COL11A1 mRNA levels relative to adjacent normal tissues (n = 30) and benign tumors (n = 30) (p < 0.001)." (PMID 39845732, 2025). "The study analyzed 40 cases of breast carcinoma in situ, of which 21 exhibited tumor microinfiltration, identified through COL11A1 immunohistochemical expression." (PMID 41462920, 2025). "The fluctuating expression of COL11A1 throughout the stages of carcinogenesis and breast cancer development implies a dual role for COL11A1 in tumor progression." (PMID 39845732, 2025). "To validate the credibility of this study, we demonstrated through real-time RT-PCR that COL11A1 mRNA expression levels are significantly elevated in primary breast cancer tissues compared to lymph node metastasis tissues." (PMID 39845732, 2025). "These immune checkpoints represent major therapeutic targets in breast cancer, and their modulation by COL11A1 underscores a potential mechanistic link between the tumor stroma and immune suppression." (PMID 41462920, 2025). "Higher expression levels of BGN, FN1, COL11A1, and SPTBN1 are linked to poorer overall survival in breast cancer patients is noticeable." (PMID 40898538, 2025). "Survival analysis showed that higher levels of BGN, FN1, COL11A1, and SPTBN1 are linked to poorer OS in patients with breast cancer." (PMID 40898538, 2025). "While much of the mechanistic understanding of COL11A1 comes from studies in ovarian, lung, and pancreatic cancers, emerging evidence suggests a similar role in breast cancer progression and therapy resistance." (PMID 41462920, 2025). "We noted that COL11A1 mRNA levels are elevated in breast cancer tissues relative to adjacent normal and benign tissues." (PMID 39845732, 2025). "A high expression of collagen type XI alpha 1 (COL11A1) has been associated with therapeutic resistance and poor outcomes in breast cancer subjects undergoing tamoxifen." (PMID 40244377, 2025). "Only through rigorous clinical validation can COL11A1 transition from an exploratory biomarker to a clinically actionable tool in breast cancer management." (PMID 41462920, 2025). "COL11A1 has been purposed as a prognostic biomarker for breast cancer as a fold change up to 5.3 was reported." (PMID 40927672, 2025). "The results revealed that MMP11+ mCAFs predominantly overlapped with FN1+ CAFs in breast cancer, COL11A1+ CAFs in colorectal cancer, and CTHRC1+ CAFs in lung adenocarcinoma." (PMID 40552583, 2025).
breast carcinoma (continued). "Clinical evidence linking COL11A1 expression to therapy resistance is currently limited, particularly for breast cancers." (PMID 41462920, 2025). "This analysis aims to elucidate the relationship between COL11A1 mRNA levels and the progression of breast cancer." (PMID 39845732, 2025). "We subsequently assessed the set of INHBA-related genes in breast cancer and found that genes encoding collagens COL10A1, COL12A1, COL5A2 and COL11A1 were associated with INHBA expression." (PMID 41008625, 2025). "In our analysis, COL11A1 mRNA expression levels were markedly elevated in breast cancer specimens relative to matched normal breast specimens (n = 30, p < 0.001)." (PMID 39845732, 2025). "This study aimed to validate previously identified variations in COL11A1 expression during breast cancer carcinogenesis and progression, as well as elucidate their clinical implications." (PMID 39845732, 2025). "Conversely, lymph node metastases (n = 30) showed significantly lower COL11A1 mRNA levels compared to their primary breast cancer counterparts (p=0.005)." (PMID 39845732, 2025). "In this study, we found that both mRNA and protein levels of COL11A1 were elevated in primary breast cancer tissues compared to normal breast tissue, yet decreased in lymph node metastases relative to primary breast cancer." (PMID 39845732, 2025). "This insight underscores the potential of COL11A1 expression profiling to enhance early detection, improve prognostic accuracy, and inform personalized treatment strategies in breast cancer management." (PMID 39845732, 2025). "This review aims to synthesize current knowledge on COL11A1 in breast cancer, focusing on its involvement in therapeutic resistance, tumor immune interactions, and its potential as a diagnostic, prognostic, or therapeutic biomarker." (PMID 41462920, 2025). "Another limitation is the absence of large, well powered clinical studies assessing the frequency of COL11A1 expression across breast cancer subtypes or defining its relationship with resistance to endocrine and chemotherapeutic therapies." (PMID 41462920, 2025). "According to two recent studies, COL11A1 also regulates immune infiltration in breast cancer, suggesting COL11A1 plays an important role in tumor immunity." (PMID 38806505, 2024). "The results of our study provide an understanding of the role of COL11A1 in breast cancer and facilitate the development of novel treatment strategies to overcome endocrine therapy resistance." (PMID 38806505, 2024). "In this study, we demonstrated COL11A1 confers tamoxifen resistance and represents a promising therapeutic target in breast cancer." (PMID 38806505, 2024). "We further conducted experiments and verified that exogenously overexpression of COL11A1 promotes breast cancer cells resistant to tamoxifen, while COL11A1 knockdown restores sensitivity of TamR cells to tamoxifen both in vitro and in vivo." (PMID 38806505, 2024). "Ectopically overexpression of COL11A1 dramatically attenuated the reduction in cell viability of breast cancer cells treated with increasing concentrations of tamoxifen." (PMID 38806505, 2024). "Together, these observations suggest COL11A1 serves as a promising therapeutic target for TamR breast cancer and inhibition of COL11A1 potentially leads to restoration of sensitivity to tamoxifen." (PMID 38806505, 2024). "We first confirmed the expression of COL11A1 in breast cancer and normal breast tissue, and found COL11A1 showed higher level in breast cancer tissue compared to the normal breast tissue by GEPIA analysis." (PMID 38806505, 2024). "We then examined the expression level of COL11A1 between ER positive breast cancer cells (MCF-7 and T47D) and tamoxifen-resistant breast cancer cells (TamR)." (PMID 38806505, 2024). "We also found that elevated COL11A1 indicates insensitivity to tamoxifen and poor prognosis in breast cancer patients." (PMID 38806505, 2024).
breast carcinoma (continued). "Here, to our knowledge, we showed for the first time that COL11A1 is highly upregulated in breast cancer cells that are resistant to tamoxifen." (PMID 38806505, 2024). "Collectively, these results suggest COL11A1 overexpression makes tamoxifen-sensitive breast cancer cells refractory to the drug." (PMID 38806505, 2024). "Colony formation experiment further confirmed COL11A1 inhibited the sensitivity of breast cancer cells to tamoxifen." (PMID 38806505, 2024). "To investigate the role of COL11A1 in tamoxifen resistance, we stably transfected tamoxifen-sensitive, ER+ breast cancer MCF-7 and T47D cells with COL11A1 plasmid, and confirmed a notable increase of COL11A1 level." (PMID 38806505, 2024). "In this study, we identified 8 cDEGs (COL11A1, COL10A1, CD36, ACACB, CD24, PLK1, UBE2C, and PDK4) as breast cancer (BC)-causing HubGs from 3 microarrays and one scRNA-seq dataset by the protein-protein interaction (PPI) network analysis of 46 cDEGs." (PMID 37893423, 2023). "An evaluation of cancer hallmark gene-sets associated with five continuous phenotypes C3, COL11A1, CXCL12, FBLN1, and S100A4 using the aspatial methods including GSEA, LCT, and RF-GSEA on a single cell breast cancer study." (PMID 36998245, 2023). "It is worth noting that among breast cancer patients with different lymph node status, only high expression of COL11A1 in patients with positive lymph node metastasis was significantly associated with poor OS of the patients." (PMID 36160004, 2022). "We identified COL11A1 as a potential therapeutic target in breast cancer through machine learning, and the high expression of this gene was generally associated with a poor prognosis." (PMID 36389832, 2022). "Recently, high levels of circulating COL11A1 have been identified in patients with non-small cell lung cancer and breast cancer, which has been correlated with increased aggressiveness of the disease." (PMID 35847935, 2022). "Third, additional clinical RCTs are needed to confirm the predictivity of COL11A1 in the immunotherapy response of breast cancers." (PMID 36389832, 2022). "Accordingly, we believe that COL11A1 under the regulation of non-coding genes and coding genes plays an important role in the occurrence and development of breast cancer." (PMID 36160004, 2022). "COL10A1 and COL11A1, as members of the collagen family, are upregulated in breast cancer fibroblasts." (PMID 35505821, 2022). "A total of 43 related immune regulation genes of COL11A1 were identified from breast cancer samples." (PMID 36389832, 2022). "Nevertheless, according to previous preliminary findings, the expression level of COL11A1 in breast cancer tissues was abnormally up-regulated, and high level of COL11A1 suggested poor prognosis of breast cancer patients." (PMID 36160004, 2022). "Fourth, the possible role of COL11A1 involved in the TME of breast cancers should be further explored through basic research studies." (PMID 36389832, 2022). "Some studies have reported that COL11A1 is highly expressed and correlated with poor prognosis in breast cancers, while its expression is low and serves as a good prognostic indicator in some hematological tumors." (PMID 36389832, 2022). "The differentially expressed genes between breast cancer patients with high COL11A1 expression and those with low expression of COL11A1 were analyzed using the R software DEseq2 package in the TCGA database." (PMID 36160004, 2022). "More interestingly, among the 4 breast cancer subtypes classified according to the expression of PAM50, the overexpression of COL11A1 in Luminal A, Luminal B, and Basal breast cancers all showed a significant impact on the prognosis of patients." (PMID 36160004, 2022). "The expression of COL11A1 is abnormally upregulated in breast cancer and is significantly related to the poor prognosis of breast cancer." (PMID 36160004, 2022).
breast carcinoma (continued). "In breast cancer, the expression of COL11A1 was significantly correlated with the expression of PD-1, PD-L1 and CTLA-4." (PMID 36160004, 2022). "And the relevant results suggested that the different expression of COL11A1 has a higher value in evaluating the adverse prognosis of breast cancer patients with lymph node metastasis and increased histological grade." (PMID 36160004, 2022). "In this paper, we reveal the prognostic value of COL11A1 in breast cancer and its tumor immune-related function through in-depth bioinformatics analysis." (PMID 36160004, 2022). "The heatmap shows the expression of the COL11A1 gene in normal breast cancer tissues and in different cancer tissues." (PMID 36389832, 2022). "Tumor immune infiltration analysis showed that the expression level of COL11A1 in breast cancer tissue was closely related to the infiltration degree of many kinds of immune cells in tumor tissue." (PMID 36160004, 2022). "The results suggested that the protein level of COL11A1 in breast cancer tissues was significantly higher than that in normal breast tissues." (PMID 36160004, 2022). "Immunofluorescence detection of clinicopathological specimens also found that the immune infiltration level of M2-TAMs in breast cancer tissues with high COL11A1 expression was significantly higher than that in breast cancer tissues with low COL1A1 expression." (PMID 36160004, 2022). "Second, single-cell sequencing data from breast cancer should be included to further clarify the relationship between COL11A1 and the TME in breast cancer." (PMID 36389832, 2022). "In order to confirm the role of COL11A1 in the tumor immune process of breast cancer, we introduced the TIMER database, and explored the correlation between COL11A1 expression level and tumor immune cell infiltration in the TIMER data." (PMID 36160004, 2022). "One study reported that COL11A1 played an imperative role in tumor cell metastasis in breast cancer." (PMID 35669376, 2022). "More importantly, COL11A1 can affect the prognosis of breast cancer patients by participating in the regulation of tumor immune infiltration." (PMID 36160004, 2022). "The purpose of this study is to elucidate the relationship between COL11A1 and breast cancer progression and immune infiltration through bioinformatics methods, and to explore its molecular regulation mechanism." (PMID 36160004, 2022). "To better understand the prognostic value and possible mechanisms of COL11A1 expression in breast cancer, we explored the relationship between COL11A1 transcription level and clinical features using the Kaplan-Meier database." (PMID 36160004, 2022). "Further overall survival analysis of COL11A1-related breast cancer patients showed that breast cancer patients with high COLL1A1 expression had worse overall survival than those with low COL11A1 expression." (PMID 36160004, 2022). "In order to clarify the impact of COL11A1 on the clinical progression of breast cancer, we conducted subgroup analysis based on lymph node status, estrogen, progesterone, histological grade and PAM50 status." (PMID 36160004, 2022). "miR-139-5p expression is low in breast cancer cells and COL11A1 is predicted to be a target gene of miR-139-5p." (PMID 35847935, 2022). "To further confirm the role of COL11A1 in the occurrence and development of breast cancer, we constructed a gene network interacting with COL11A1 in GeneMania database, and listed the top 20 genes closely related to COL11A1." (PMID 36160004, 2022). "Aside from ovarian/breast cancer cells, sarcoma cells, and fibroblasts, a few other studies have documented how COL11A1 transcription is regulated in osteocytes and myoblasts." (PMID 33668097, 2021). "miR-139 inhibits proliferation through translational repression of COL11A1, leading to the upregulation of Bax and activation of Caspase 3-mediated apoptosis of breast cancer cells." (PMID 34070538, 2021).
breast carcinoma (continued). "In xenograft mouse models of breast cancer, COL11A1 expression is negatively regulated by transcription factor CDX2 and microRNA let-7b and the loss of COL11A1 expression by upregulating CDX2 let-7b suppressed metastasis." (PMID 33668097, 2021). "Another study mentioned that miRNA let-7b is a tumor suppressor and let-7b can inhibit COL11A1 expression, thereby reducing the proliferation, invasion, and migration of breast cancer cells." (PMID 34944877, 2021). "Another microRNA, miR-139-5, has also been shown to suppress COL11A1 expression in the breast cancer cell line ZR-75-1." (PMID 33668097, 2021). "Overall, the current study verified the CDX2/let-7b/COL11A1 modulation in breast cancer epithelial cells, and investigated the tumor growth and metastasis through in vivo models." (PMID 31938021, 2020). "With our research, our endeavor is to explore the role of the CDX2/let-7b/COL11A1 axis in breast cancer cell activities." (PMID 31938021, 2020). "We also identified different collagen proteins (such as COL10A1 and COL11A1) that are up-regulated in luminal versus normal breast cancer samples." (PMID 30835723, 2019). "In our study, breast cancers with suspicious calcifications had low expression of COL11A1 and FNDC1." (PMID 28900139, 2017). "COL11A1 is down-regulated in breast cancers with highly suspicious calcifications compared to those with low-to-intermediate suspicious calcifications (p = 0.002) and those without suspicious calcifications (p = 1.98E-06)." (PMID 28900139, 2017). "First, breast cancers with highly suspicious calcifications are associated with high levels of mRNA expression of ERBB2 and decreased expression of COL11A1 and FNDC1." (PMID 28900139, 2017). "In a significant study for breast cancer, COL11A1 is shown to be significantly upregulated in infiltrating tumor lesions compared to their in situ compartments and adjacent stroma." (PMID 26466668, 2015). "Furthermore, we examine COL11A1 protein expression in six sets of matched samples encompassing adjacent normal breast, primary breast cancer, and lymph node metastasis tissues." (PMID 39845732, 2025). "Notably, 96.9% (29/30) of adjacent normal breast tissues and 83.3% (25/30) of benign tumor tissues exhibited low COL11A1 mRNA expression levels, in contrast to 81.3% (87/107) of primary breast cancer samples which demonstrated high COL11A1 mRNA expression." (PMID 39845732, 2025). "Notably, within the same cohort of patients, a rise in COL11A1 mRNA levels was documented from the matched normal breast to primary breast cancer, with a subsequent decline from the primary breast cancer to the matched lymph node metastasis tissues (n = 10)." (PMID 39845732, 2025). "Our findings suggest that COL11A1 might function as a metastasis suppressor in the advanced stages of breast cancer progression, highlighting its potential role in the complex dynamics of tumor spread." (PMID 39845732, 2025). "Furthermore, recent investigations employing microarray technologies have consistently identified COL11A1 overexpression in several cancer types (such as breast cancer, lung adenocarcinoma, and hypopharyngeal cancer) versus their corresponding normal tissues." (PMID 39845732, 2025). "On the one hand, the dynamic shifts in COL11A1 expression could be driving factors behind the advancement of breast cancer." (PMID 39845732, 2025). "Notably, COL11A1 expression levels in breast cancer tissues surpass those in normal breast tissues, a finding corroborated by protein level assessments in breast cancer tissues versus normal breast tissues from the CPTAC database." (PMID 39845732, 2025). "Plasma level of collagens, especially the COL11A1, has been reported to elevate in breast cancer." (PMID 40927672, 2025). "Moreover, analyses of 20 pairs of breast cancer patient samples revealed that both mRNA transcription and protein expression levels of COL11A1 are significantly elevated in cancer tissues compared to adjacent nontumorous tissues." (PMID 39845732, 2025).